HGF (hepatocyte growth factor)
Diseases named in the same sentence as HGF in open-access papers (continued):
Sharing a sentence is not in itself a finding about the gene and the disease.
tumor (continued). "The paracrine loop between HGF-producing stroma and MET-expressing tumor cells acts as a local switch for the invasive phenotypes, as follows." (PMID 23296269, 2013). "We also demonstrated temporal local and systemic changes in growth factors (HGF, VEGF, and TGF-β) that are also known to be pro-angiogenic and support tumor growth." (PMID 24403226, 2013). "There are now numerous reports showing that HGF-antagonists and MET-inhibitors are logical for inhibiting tumor growth and metastasis." (PMID 23296269, 2013). "Following treatment the concentration of HGF and VEGF significantly increased in the tumor lysates at 24 h and returned to base levels by day 5 confirming our immunohistochemistry results for VEGF." (PMID 24403226, 2013). "Take these results together with our finding of endocan expression in NPC tumor cells, it is possible that endocan secreted from NPC cells can enhance the effect of HGF/SF on the growth and metastasis of NPC." (PMID 24340011, 2013). "For this purpose, tumor cells acquire MET via the HIF-dependent pathway, while stroma-secreted HGF enhances cell motility from hypoxic regions to the aerobic milieu of distant organs (i.e., successful metastasis)." (PMID 23296269, 2013). "Among the tumor supportive factors potentially secreted by TAMs, TGF-β, EGF, and HGF/SF have drawn the most attention, though dissecting the precise role of TAMs in the production of these trophic factors remains to be accomplished." (PMID 23737783, 2013). "The EMT program can be activated by a multitude of factors secreted by tumor stroma cells, which triggers a complex signaling network including TGF-β, Wnt, HGF, EGF, and PDGF pathways." (PMID 23898462, 2013). "Apart of its role in tumor pathogenesis, MET/HGF deregulated function emerges as an important resistance mechanism to targeted therapies against other oncogene systems such as that of the epidermal growth factor receptor (EGFR)." (PMID 24378750, 2013). "Even if NK4 enhances tumor hypoxia via the inhibition of tumor angiogenesis, hypoxia-mediated metastasis will be avoidable, because NK4 can counteract HGF-mediated metastatic events (see Section 5.1)." (PMID 23296269, 2013). "SDF-1-CXCR4, HGF-Met, Shh-Smo, PDGF-PDGFR and TGFβ-TGFβR signalling pathways or HA ECM protein have been reported to mediate the CAF-tumour(stroma)cellinteractions." (PMID 24216702, 2013). "The antibodies targeting HGF are L2G7 (Galaxy Biotech), AMG102 (Amgen), OA-5D5 (Genentech), and CE-3556221 (Pfizer) that can inhibit tumor angiogenesis by blocking the binding of HGF/c-Met." (PMID 21876694, 2012). "MET, a tyrosine kinase, and its ligand, hepatocyte growth factor (HGF), play a pivotal role in tumor cell proliferation, survival, and metastasis." (PMID 23554766, 2012). "One way this occurs is through tumor cell secretion of soluble factors, such as IL-1, FGF-2, PDGF, and/or TGF- β, which induce hepatocyte growth factor (HGF) secretion from fibroblasts." (PMID 22438903, 2012). "It was found that expression of IGF1, HGF, PDGFC, and PDGFD were significantly increased 5.32-, 10.21-, 6.24-, and 3.24-fold in tumor tissues, respectively, when compared with arachnoidal tissue by qRT-PCR." (PMID 23285163, 2012). "HGF induction of Rac1 activation and MT1-MMP production implied that cell migration and proteolysis are two essential processes during tumor invasion and metastasis." (PMID 22242160, 2012). "Some postulated theories include varying hepatocyte growth factor (HGF), VEGF receptors or serum levels, decreased drug bioavailability in certain organs, and organ-specific tumor resistance." (PMID 22007339, 2011). "Novel antibody proximity-based assays were developed and used to detect and quantify total c-MET, total HGF, and HGF-c-MET ligand-receptor interactions in FFPE cell line and tumor tissue." (PMID 21283737, 2011).
tumor (continued). "Among the tumour invasion-inducible factors, transforming growth factor (TGF)-β1, hepatocyte growth factor (HGF), and Ln5-γ2 have been reported to be involved in cutaneous SCC tumorigenesis." (PMID 21829200, 2011). "Specific inhibition of MET phosphorylation with small molecule inhibitors has demonstrated the capacity of counteracting the HGF induced effects in SCLC and other tumour models." (PMID 21847116, 2011). "With regard to the paracrine pathway, IL-6-stimulated stromal cells promoted the secretion of tumor growth and adhesion molecules containing VEGF and hepatocyte growth factor (HGF)." (PMID 19457231, 2009). "Macrophages recruited to hypoxic sites exert a tumor-promoting effect through the expression of genes with mitogenic, angiogenic, and migration/invasion stimulating properties, such as VEGF, EGF, or HGF." (PMID 19536297, 2009). "The HGF and EGF staining by IHC were present at concentrated amounts on the leading edge of tumor where a large portion of stroma is found in the admixed Skov-3/MSC tumors as compared to the Skov-3 only tumors." (PMID 19352430, 2009). "The reciprocal regulation of MSC conditioning on stimulated Skov-3 tumor showed increases in IL-6, TGF-β, VEGF and HGF secretion." (PMID 19352430, 2009). "Expression of c-Met and HGF in NBL cell lines SH-EP and SH-SY5Y and primary tumor tissue was assessed by immunohistochemistry and quantitative RT-PCR." (PMID 19939254, 2009). "The presence of MSC within the tumor also enhanced expression of growth factors such as EGF and HGF." (PMID 19352430, 2009). "We confirmed the presence of HGF, EGF and IL-6 within the tumor stimulated MSC population that we identify as TAF." (PMID 19352430, 2009). "Hepatocyte growth factor (HGF), through Met receptor binding, fulfils numerous functions in invasive tumour growth (survival/proliferation, motility, apoptosis), but epigenetic control of gene expression in this process is poorly understood." (PMID 18941460, 2008). "We found that CSCs, in comparison with H460 tumor cells, produced up to two to threefold higher level of angiogenic and growth factors (VEGF, PDGF-BB, bFGF, IGFBP-β, and HGF)." (PMID 18728788, 2008). "To understand better the role of the in vivo c-MET/HGF signalling in SCLC tumour tissues, we performed IHC analysis in SCLC tumours, as established on a tissue microarray." (PMID 17667909, 2007). "A number of reports demonstrated that over-expression of Sulf-1 or Sulf-2 in tumor cell lines inhibited growth factor signaling in response to several factors, including FGF-2, HB-EGF, and HGF." (PMID 17460759, 2007). "With tumour tissue microarray (TMA) and phosphoantibody immunostaining, we also gained further insight into the role of c-MET/HGF signalling in SCLC biology and tumour invasion." (PMID 17667909, 2007). "Various growth factors and their receptors, including hepatocyte growth factor (HGF)/c-Met, epithelial growth factor (EGF)/EGF-R, and the vascular endothelial growth factor (VEGF) family/VEGF-Rs, are reported to be involved in tumour–stromal interactions." (PMID 15083185, 2004). "A key discovery was a substantial increase in the secretion of LIF (leukemia inhibitory factor) and HGF (hepatocyte growth factor) in heterotypic spheroids with CAFs (BrC4f), irrespective of the molecular type of tumor cells." (PMID 41597220, 2026). "Several studies have also demonstrated the formation of complexes between c-Met and integrins such as α5β1, α3, and α6β4 in tumor cells, both in the presence and absence of HGF." (PMID 41511363, 2026). "ENKTCL-derived or tumor-educated MSCs can produce a range of growth factors and extracellular matrix components that facilitate tumor cell proliferation, invasion and survival, such as VEGF, hepatocyte growth factor (HGF) and stromal-derived factor 1 (SDF-1/CXCL12)." (PMID 41303704, 2025).
tumor (continued). "Once activated, CAFs secrete various bioactive molecules, including growth factors (e.g., vascular endothelial growth factor [VEGF], hepatocyte growth factor [HGF]), chemokines (e.g., CXCL12, CXCL5), and ECM proteins, thereby promoting tumor cell survival, angiogenesis, and immune evasion." (PMID 40656546, 2025). "Meanwhile, TAMs foster cancer progression by interacting with TME or by secreting growth factors such as epithelial growth factor (EGF), platelet-derived growth factor (PDGF), TGF-β, hepatocyte growth factor (HGF), basic fibroblast growth factor (bFGF) that stimulate tumor proliferation." (PMID 40083710, 2025). "Recruitment and activation of quiescent tissue-resident fibroblasts into CAFs involves a variety of tumor-cell-derived activators and modulators, including TGFβ, fibroblast growth factor 2 (FGF-2), hepatocyte growth factor (HGF), PDGF, stromal-derived factor-1 (SDF-1) and signaling pathways." (PMID 40805183, 2025). "Moreover, research by the Finisguerra group revealed that HGF interacts with the MET receptor on neutrophil surfaces, thereby activating the iNOS signaling axis and promoting NO production, which enhances tumor cell cytotoxicity." (PMID 40564191, 2025). "Unlike myCAF, iCAF is enriched in early stage ICC and promotes ICC development through the hepatocyte growth factor (HGF)-MET (HGF receptor) axis as a key tumor-promoting ligand–receptor pair, directly linking iCAF to tumor cells via ERK-mediated tumor cell proliferation." (PMID 40248197, 2025). "In addition to promoting tumour progression through enhanced cell proliferation and migration, the HGF/MET pathway also modulates the function and infiltration of immune cells within the tumour microenvironment, thus contributing to immune evasion." (PMID 40599602, 2025). "HGF is a widely distributed growth factor and our findings on its oncogenic function may be applicable not only to CCA, but also to other tumor types." (PMID 41048570, 2025). "By using next-generation sequencing and other techniques on CCA tumor tissues and cells, we demonstrated the molecular mechanism by which CAFs in the tumor microenvironment promote the proliferation, invasion, and migration of CCA cells via HGF mediation." (PMID 41048570, 2025). "To verify the bioinformatic findings, we performed immunohistochemical staining for HGF and HRH2 on tumor tissues from iCCA (n = 10), pCCA (n = 10), and dCCA (n = 10), with subsequent correlation analysis showing a positive correlation between their expression." (PMID 41048570, 2025). "In the context of NAFLD, the reduction of hepatic sinusoidal perfusion may lead to an increase in the release of various angiogenic inducing factors such as HGF, HIF - 1, VEGF, thereby inducing angiogenesis and further promoting tumor growth." (PMID 40994954, 2025). "Neutrophils, particularly those polarized toward the N2 phenotype, are key contributors to tumor angiogenesis through the secretion of multiple pro-angiogenic factors, including FGF2, VEGF-A, ANGPT1, CXCL8, HGF, and MMP9, which collectively facilitate tumor vascularization and metastatic spread." (PMID 40564191, 2025). "The HGF-MET signaling has been extensively reported to participate in the tumorigenesis, metabolism and metastasis of various cancers, and multiple HGF-MET pathway inhibitors exhibited potent anti-cancer role by preventing tumor metastasis." (PMID 41234356, 2025). "SRC plays a multifaceted oncogenic role in CCA by activating key signaling pathways, interacting with FAK in response to HGF to promote proliferation and invasion, forming a metastatic SRC–Hic-5–AKT cascade, and phosphorylating YAP to drive tumor growth and therapy resistance." (PMID 41300430, 2025). "Interestingly, while PI3K signaling was essential for HGF-induced invasiveness in both lines, the importance of ERK1/2 in promoting tumor invasion was related to the duration of ERK1/2 activation." (PMID 40723336, 2025).
tumor (continued). "Cells with heightened receptor expression demonstrated an escalated production of cytokines and growth factors (e.g., interleukin-1 beta (IL-1β), hepatocyte growth factor (HGF), interleukin-8 (IL-8), VEGF), which were found to provide notable support to tumour progression." (PMID 41301715, 2025). "The HGF/c-MET signaling axis contributes to modulating the liver’s microenvironment through various processes, including ECM remodeling, inflammation, angiogenesis, and invasion, to promote tumor progression and metastasis." (PMID 40304568, 2025). "Interestingly, while TAS-115 reduced the survival of tumor cells, it appeared to support NHLF viability, as indicated by HGF expression." (PMID 41289612, 2025). "Consistent with the lack of impact of HGF on the baseline proliferation of H3122 cells both in vitro and in vivo, we observed no discernable differences in tumor implantation efficiency and baseline tumor growth." (PMID 40313737, 2025). "Beyond remodeling, CAFs also secrete a broad range of growth factors, including hepatocyte growth factor (HGF), fibroblast growth factor (FGF), insulin-like growth factor 1 (IGF-1), and TGF-β, which drive tumor cell proliferation and induce epithelial-to-mesenchymal transition." (PMID 40871003, 2025). "Consistent with the lack of detectable HGF-dependence on the initial tumor responses, we did not detect differences in the stroma proximity bias between the NSG and NSGhHGF tumors during remission." (PMID 40313737, 2025). "While Ang-2 and HGF were elevated, we did not assess their in vitro activity on endothelial or tumor cells." (PMID 40867270, 2025). "Therefore, inhibiting HGF overexpression and affecting MET activation appears to be a reliable approach to intervening in the treatment resistance of LUAD and suppressing tumor growth." (PMID 40136462, 2025). "Similarly, engineering NSCs to express higher levels of chemokine receptors, such as CXCR4 and c-Met, augments their responsiveness to tumor-derived chemotactic signals (e.g., CXCL12, hepatocyte growth factor), thereby enhancing tumor tropism." (PMID 41264121, 2025). "In addition, activation of the MET signalling pathway, mediated by the receptor tyrosine kinase MET and its ligand hepatocyte growth factor (HGF), enhances neutrophil NO release, which amplifies oxidative stress and promotes tumour cell killing." (PMID 41451221, 2025). "There is a tumor suppressor role for SULF1, being an extracellular sulfatase that removes 6-O-sulfate groups from heparan sulfate (HS) chains, thereby reducing the activity of HS-binding growth factors such as FGF2, VEGF, amphiregulin, HB-EGF, and HGF." (PMID 41373732, 2025). "These include ECM proteins like collagen, MMPs (MMP-2, -9, and -13), angiogenesis-related factors (VEGF), growth factors (TGF-β, HGF), and chemokines such as CXCL-8 and IL-6, which affect tumor cell growth, metastatic potential, drug resistance, and CSC self-renewal." (PMID 40399946, 2025). "Moreover, hepatocyte growth factor (HGF) and its receptor, mesenchymal epithelial metastasis factor (c-Met) play a role in various tumor progression and metastasis." (PMID 38935609, 2024). "TAN promote tumor invasion and angiogenesis, as well as migration, through the production of matrix metalloproteinase-9 (MMP-9), vascular endothelial growth factor (VEGF), and hepatocyte growth factor (HGF) at both primary and metastatic sites." (PMID 39100676, 2024). "Additionally, CAFs secrete growth factors like TGF-β, IL-6, and hepatocyte growth factor (HGF), which promote tumor proliferation and angiogenesis." (PMID 39200315, 2024). "In agreement, senescent fibroblasts express various proliferation-inducing factors (e.g. HGF, CXCL12 and EGF), can induce treatment resistance via inducing tumor cell EMT, or metabolically support tumor cell progression and metastasis by upregulating glycolysis and ketone production." (PMID 39696386, 2024).
tumor (continued). "This review explores the biological functions of the HGF/c-MET signaling pathway in both normal and cancerous cells, examining its multifaceted roles in the NSCLC tumor microenvironment, including tumor cell proliferation, migration and invasion, angiogenesis, and immune evasion." (PMID 39201787, 2024). "In addition, Cadranel and colleagues found that bronchoalveolar lavage fluid from BCA patients contained a high concentration of biologically active HGF, which promoted the migration of BAC tumor cells." (PMID 39201787, 2024). "Previous studies have indicated that the HIF-1α in the tumor microenvironment promotes the expression of VEGF, HGF, met proton genes, and induces the degradation of extracellular matrix, which is involved in the mechanism of cancer cell metastasis known as EMT." (PMID 38689341, 2024). "Once recruited, MDSCs cluster around the original tumor, promoting EMT, creating cancer stem cell-like cells, and disseminating cancer cells through the activation of TGF-β, COX2, and the secretion of EGF and HGF." (PMID 38244071, 2024). "Therefore, activation of the HGF-MET and GAS6-AXL pathways promotes tumor survival, proliferation, infiltration, and metastasis, and blocking VEGF can lead to MET and AXL activation." (PMID 38289361, 2024). "Notably, a significant rapid rise in tumor- and metastases-promoting molecules such as matrix metalloproteinase-9 (MMP-9), interleukin-6 (IL-6), hepatocyte growth factor (HGF), and placental growth factor (PLGF) was observed immediately (2 h) after surgery." (PMID 39451257, 2024). "Collectively, HGF/c-MET signaling plays a pivotal role in the formation and maturation of new blood vessels, ultimately facilitating the essential blood supply required for tumor progression and metastasis." (PMID 39201787, 2024). "We found that tumor cells but not Iba1high TAMs that resided in tumor cell-free adjacent stroma showed activation of MET, however, MET was also activated in the absence of adjacent microglia in some tumor cells, suggesting a paracrine effect of HGF." (PMID 38386085, 2024). "Furthermore, the HGF/c-MET pathway stimulates angiogenesis, ensuring an adequate blood and nutrient supply to the tumor, thus fostering further growth and expansion." (PMID 39201787, 2024). "As we observed that HGF is expressed by immune cell subsets and homeostatic or reactive astrocytes and microglia, we investigated the level of activated/phosphorylated MET receptor in TAM-adjacent tumor cells." (PMID 38386085, 2024). "In addition, HGF, a MET ligand secreted mainly from mesenchymal cells in tumor tissues, exerts a wide array of physiological effects, including promoting tumor cell proliferation and inhibiting tumor cell apoptosis." (PMID 38289361, 2024). "Additionally, HGF/c-MET signaling promotes the migration and invasive capabilities of tumor cells, facilitating local invasion and distant metastasis." (PMID 39201787, 2024). "Circ-HGF RNA junction reads in ribosome profiling experiments were detected in all four primary GBM tumor samples tested and not found in any of the normal brain samples (top)." (PMID 37162666, 2023). "Propofol decreased hypoxia inducible factor 1α (HIF1α), interleukin 1β (IL1β), and hepatocyte growth factor (HGF) gene expressions and increased tissue inhibitor of metalloproteinases 2 (TIMP-2) gene and protein expression in comparison to sevoflurane in the tumour tissue." (PMID 35953652, 2023). "Some Mabs target EGFR, HER2, IGF‐1R, HGF, and VEGF; others may be checkpoint inhibitors (including Mabs to PD‐1, CTLA4, and NKG2A) or tumor‐targeting Mabs such as U36 and Mab E48." (PMID 37042307, 2023). "Neutrophils could also produce some secreted factors, such as epidermal growth factor (EGF), hepatocyte growth factor (HGF) and platelet-derived growth factor (PDGF) to sustain tumor proliferation." (PMID 36934105, 2023).